CCR2 (C-C motif chemokine receptor 2)
Diseases named in the same sentence as CCR2 in open-access papers (continued):
Sharing a sentence is not in itself a finding about the gene and the disease.
infection (continued). "Knocking out CCR2 has been shown to significantly reduce virus binding and infection, while increased expression of CCR2 leads to enhanced infection." (PMID 38812521, 2024). "Though all three of these ligands bind to CCR2, they had vastly different expression levels through the course of infection." (PMID 38352492, 2024). "In the WNV mouse model, CCL2 and CCL7 are important ligands for CCR2 and affect monocyte infiltration to the CNS; however, only CCL7 deficiency is associated with increased sensitivity to infection." (PMID 38997413, 2024). "Here we examined iMOs recruited to the brain during a CCR2-independent (LACV) versus a CCR2-dependent (HSV-1) infection for GPCR transcript expression." (PMID 38658802, 2024). "The brains were harvested at 15 DPI, which is an acute infection timepoint that represents the peak of CCR2+ monocyte infiltration to the brain in our model." (PMID 38206985, 2024). "In CCR2-depleted mice, lung monocyte concentrations remained consistently low throughout the infection process, with less than 10,000 cells/mL at each time point." (PMID 39418302, 2024). "Using a CCR2-DTR transgenic mouse model we demonstrate that over the course of infection monocyte depletion resulted in worse airway clearance of S. aureus." (PMID 39418302, 2024). "When graphed continuously, over time CCR2-DTR mice fair much poorer in their capacity to clear the infection." (PMID 39418302, 2024). "Despite the excessive number of neutrophils in the liver, spleen, and blood of Ccr2–/– mice, these mice are unable to clear the infection and ultimately succumb." (PMID 39541153, 2024). "The chemokine receptor CCR2 controls the release of CD11b+Ly6Chigh monocytes from the bone marrow and their recruitment to the sites of infection or inflammation." (PMID 39506629, 2024). "The role of CCR2 during M. tuberculosis infection is strain-dependent, and also varies depending on the dose and route of infection." (PMID 38352492, 2024). "In contrast to the effector function of CCR2+ TVM cells in the early phase of infection, CCR2- TVM cells have a higher capacity to differentiate into CD103+ CD69+ TRM cells in the lung tissue than TN cells." (PMID 39193473, 2024). "In this experiment, WT and CCR2-depleted mice were infected intranasally with S. aureus and, 24 h post infection, alveolar macrophages (AM), neutrophils and monocytes were collected from the lungs by fluorescence activated cell sorting." (PMID 39418302, 2024). "In response to inflammatory signals during infection, Ly6Chi CCR2+ monocytes expand in the bone marrow and are recruited to sites of infection." (PMID 37965344, 2023). "Their elevated levels of the migratory receptor CCR2 facilitate their exit from the bone marrow and rapid movement to sites of inflammation or infection." (PMID 37818368, 2023). "CCL2, which drives macrophage differentiation during inflammatory response is also locally expressed in inflamed lungs and helps recruit CCR2+ monocytes from the circulation during PR8 infection." (PMID 36845136, 2023). "Although, we observed an overall decrease in the alveolar macrophage population in the BALF of both WT and S100A8/A9, there was a significant increase in number of infiltrating inflammatory macrophages (F4/80+ CCR2+ cells) in S100a9 KO mice upon infection." (PMID 37624851, 2023). "Bone marrow–derived monocytes are recruited to the lung during infection in a C-C chemokine receptor type 2–dependent (CCR2-dependent) manner." (PMID 36928191, 2023). "CCR2+ inflammatory monocytes were less frequent in the infected LNs and showed very low levels of infection/co-localization with the mChLgyLRV1+ parasites present within the organs, as observed earlier for neutrophils as well." (PMID 36034709, 2022). "Upon PVM inoculation, a significant increase in IL-6 production was detected in mock-primed WT and CCR2−/− mice, starting at 12 h post infection and continuously increasing to the last measure applied 72 h post inoculation." (PMID 35062301, 2022).
infection (continued). "Secondly, virulent mycobacteria (such as M. marinum) exploit a unique lipid effector, phenolic glycolipid (PGL), to secrete CCL2, a chemokine ligand for CCR2, which recruits permissive macrophages to the infection site in a STING–CCL2–CCR2-dependent manner." (PMID 35603185, 2022). "The analyses revealed that, compared to the H7N9 infection, the H9N2 infection induced an earlier induction of both CCR2 and CXCR4 transcripts, similar to that of CCL2 in the lung (data not shown)." (PMID 36034707, 2022). "Numerous trained immunity studies focus on monocytes, however our work previously showed that MPLA-induced resistance to infection is preserved in CCR2 knockout mice which have defective monocyte recruitment." (PMID 36439136, 2022). "In contrast, the innate immune system consisting of lung AECII and CCR2+ monocytes have important functions combating acute high-dose infection with this replicative DNA virus." (PMID 35351885, 2022). "The proportion of CCR2+ cells in the separated cells showed a noteworthy increase on the 7th day in the ECM brain compared with that in the normal group (p = 0.0032), and the quantity of CCR2+ cells also increased after infection (p = 0.0202)." (PMID 34766463, 2022). "Above results further confirmed innate immunity mediated by lung AECs in response to VACV∆C7L infection is important for CCR2+ monocytes activation and their differentiation into Lyve1− IMs, which are crucial to restrict vaccinia virus infection in the lungs." (PMID 35351885, 2022). "Taken together, our results indicate that intranasal infection of VACV∆C7L leads to the recruitment of CCR2+ monocytes into the lungs, which can further differentiate into Lyve1− IMs and DCs under the influence of an inflammatory milieu in the infected lungs." (PMID 35351885, 2022). "During vaccinia virus infection, we found that CCR2+ inflammatory monocytes are indispensable for protection against VACV∆C7L infection." (PMID 35351885, 2022). "The chemokine receptors CCR2 (CCL2/MCP-1 receptor) and CCR5 (CCL3/MIP-1A receptor) in deficient mice exhibit defects in directing inflammatory cells to airways after infection." (PMID 36119044, 2022). "Three days after infection, we detected remarkably upregulated expression of CCR2 at the mRNA and protein levels in MSCCCR2 through qRT-PCR and Western blotting, respectively." (PMID 35123561, 2022). "Inflammatory monocytes can rapidly recruit and migrate to the region of injury or infection via C-C chemokine receptor type 2 (CCR2), C-C motif chemokine ligand 2 (CCL2), monocyte chemotactic protein-1 (MCP-1), and C-X-C motif ligand 10 (CXCL10)." (PMID 35669508, 2022). "Lm killing and vaccinated host protection during recall infection require TNFα, which CCR2+Ly6C+ monocytes are a major source." (PMID 34516896, 2021). "The immune response against the HSV-1 in the murine ENS appears highly coordinated and characterized by the activation of the innate immune system at the early time of infection when macrophages are recruited in the ENS by the CCL2/CCR2 pathway." (PMID 34094993, 2021). "In our i.d. model of Orientia infection, we showed that CCR2 was required to reduce infection in the lung." (PMID 34290699, 2021). "Newly-generated cDCs expressing CCR2 are retained at foci of infection by CCL2 until they contact virus or virus-infected cells, which act as a source of antigen and activation signals." (PMID 34739343, 2021). "Our results show that cognate Ag on DCs mediates CD8+ TM cell arrest in infection foci where blood-derived CCR2+Ly6C+ monocytes have accumulated via CD8+ TM cell–independent chemotactic cues." (PMID 34516896, 2021). "The shift towards a Th2 immune response in CCR2-/- mice has been reported for infection by L. major and L.a." (PMID 34557194, 2021). "Tip-DCs derived from Ly6Chi monocytes contribute to innate defense against L. monocytogenes; hence, infection is worse in mice deficient in CCL2 and CCL7 or in Ccr2-/- mice due to an increased bacterial burden." (PMID 33829283, 2021).
infection (continued). "BothCCL2 and CCL7 and their receptors were downregulated.CCL2 and its receptors, CCR2 andCCR4, act to recruit monocytes and macrophages to the site of infection.The majority of chemokines were significantly up-regulated." (PMID 32347041, 2021). "Studies have begun to identify host specific pathways and factors that are involved in CS induced infection pathogenesis, such as CCR2, IL-17 and MAP3K19, and thus represent exciting immediate potential therapeutic targets for treatment." (PMID 34959590, 2021). "Together, these data indicate that expansion of the lung cDC network by pre-cDCs recruited via CCR2 to infection foci is necessary to support the effective generation of effector and memory T cell responses against IAV that protect from re-infection." (PMID 34739343, 2021). "Pre-cDCs acutely released from BM in a CCR2-independent manner circulate via blood and extravasate from lung capillaries adjacent to foci of infection in response to CCR2 ligands." (PMID 34739343, 2021). "Increasing LVS doses resulted in more rapid times to death of infected CCR2 KO mice, which ranged between 5 and 11 days after infection." (PMID 33760886, 2021). "The murine infection model for the disease is characterized by CCL2/CCR2-dependent recruitment of Ly6Chi monocytes to the liver, and an increase in granuloma-associated resident CX3CR1+ macrophages." (PMID 33829283, 2021). "During infection and inflammation, Ly6C+ monocytes are rapidly released from the bone marrow in a CCR2-dependent manner and recruited to infected tissues." (PMID 33593983, 2021). "We also found that CD8+ TM cell–derived signals are essential to make CCR2+Ly6C+ monocytes responsive to chemokine signals and that CCR2+Ly6C+ monocytes are only responsive to chemokines after infection." (PMID 34516896, 2021). "CCR2 KO mice succumbed to infection with doses as low as 102 LVS ID, and 70% of CCR2 KO mice given a dose of 104 LVS ID died between 8–10 days after infection." (PMID 33760886, 2021). "Compared to IL-27R−/− mice, CCR2RFP/RFP IL-27R−/− mice survived significantly longer during infections with T. congolense or T. brucei, suggesting that disruption of CCR2 signaling prevented the early mortality of infected IL-27R−/− mice." (PMID 33593983, 2021). "Our results show that, in the i.d. infection model, the CCR2-independent macrophage response, albeit delayed, is eventually sufficient to control Orientia infection in the lung." (PMID 34290699, 2021). "S2B), developed comparable numbers and volume of CCR2+Ly6C+ monocyte clusters 16 hours after infection." (PMID 34516896, 2021). "In early time points of infection in the WT mice and through the observed time course in CCR2−/− mice, we see high fungal burdens but very few neurological symptoms and relatively little inflammation." (PMID 34311579, 2021). "Here we used murine infection with the Live Vaccine Strain (LVS) of Francisella tularensis to evaluate the role of CCR2 during primary and secondary parenteral responses to this prototype intracellular bacterium." (PMID 33760886, 2021). "Despite nearly identical infection kinetics, infected CCR2 KO mice exhibited significantly less uterine horn pathology than C57BL/6." (PMID 34526512, 2021). "Nonetheless, CCR2 knockout mice vaccinated by infection with low doses of LVS generated optimal T cell responses that controlled the intramacrophage replication of Francisella, and LVS-immune CCR2 knockout mice survived maximal lethal Francisella challenge." (PMID 33760886, 2021). "Already by 3 hours after challenge infection, few clusters of CCR2+Ly6C+ monocytes were detected, with proportions increasing from 6 hours to peaking at 16 hours and with some clusters still present by 40 hours." (PMID 34516896, 2021). "Recruitment and NK cells’ activation at the site of infection requires chemokines (ligands for CCR2, CCR5, and CXCR3) and cytokines (IL-12 and IL-18) secreted from myeloid cells, mainly monocytes and macrophages." (PMID 34305935, 2021).
infection (continued). "By day 6 after infection, CCR2 KO mice given a dose of 104 LVS ID had ~ 100-fold more bacteria in spleens, livers, and lungs than the corresponding C57BL/6J mice." (PMID 33760886, 2021). "The eosinophils disappeared from the lungs upon infection and reappeared during resolution in the CCR2 WT mice." (PMID 33664739, 2020). "By immunohistochemistry, we observed large numbers of CCR2+ cells throughout the brain 4 weeks post-infection in wildtype mice." (PMID 33108405, 2020). "The number of iMOs and ncMOs in the spleen similarly decreased in CCR2 KO and WT mice upon infection (8 and 9 days p.i.)." (PMID 33664739, 2020). "Levels of IL-1β, IL-6, CCL2, CCL3, CXCL1, and CXCL2 were significantly greater 6 h following infection than in mock-infected mice (P < 0.05) but were similar among wild-type, CCR2−/−, and Nr4a1−/− mice." (PMID 31818962, 2020). "Ccr2 is required for monocyte infiltration to an infection site, and Ccr2−/− mice are also used to interrogate the function of these cells at sites of inflammation." (PMID 31932292, 2020). "CC‐chemokine receptor 2 (CCR2) gene expression was significantly increased in isolated monocytes at day 8 of blood‐stage infection." (PMID 32566226, 2020). "CCR2 is known to recruits monocyte to the intestine and promotes the accumulation of activated macrophage as a response infection with gastrointestinal parasitic helminth." (PMID 33048942, 2020). "During infection and inflammation, Ly6Chi monocytes are rapidly recruited to tissues in a CCR2-dependent manner." (PMID 32101593, 2020). "Intriguingly, our previous work showed that infection with fbp1Δ induces the increased recruitment and maturation of CCR2+ monocytes, and that these cells were required for protection from infection with fbp1Δ." (PMID 31772051, 2019). "After infection, CCR2+ migratory macrophages were polarized to the M1 phenotype and CCR2- resident macrophages remained mostly M0 (unpolarized), but almost 50% switched to the M2-like phenotype." (PMID 30998796, 2019). "We therefore infected as before, via the footpad route, CCR2-/- mice and quantified the mCMV-specific T cell in adipose at an early memory timepoint post infection, greater than 30d p.i.." (PMID 31220189, 2019). "Trafficking of Ly6Chi inflammatory monocytes to infected organs including the kidney and spleen was severely reduced 24 h post-infection in Ccr2 KO mice." (PMID 31242262, 2019). "Imaging of reporter mice also revealed induction of MCP-1 and CCR2 expression in sacral dorsal root ganglia following SΦ874 infection." (PMID 29739958, 2018). "Infection with the fbp1Δ mutant induces a rapid influx of CCR2+ monocytes and their differentiation into monocyte-derived dendritic cells (mo-DCs)." (PMID 29317510, 2018). "CCR2+ monocytes are precursors of monocyte-derived macrophages and dendritic cells (mo-DCs) that are important for controlling multiple infections." (PMID 29317510, 2018). "Here, using a biosensor for measuring pathogen proliferation in the living tissue, we found that monocyte-derived Ly6C+CCR2+ phagocytes expressing CD11c constituted the main cell type harboring rapidly proliferating L. major in the ongoing infection." (PMID 30346994, 2018). "We also observed a reduction in pelvic pain when mice infected with E. coli SΦ874 or the clinical E. coli strain NU23 were treated with a CCR2 antagonist two weeks post-infection." (PMID 29739958, 2018). "Interaction between CCR2 and its CC-chemokine ligand recruits monocytes to sites of infection and these monocytes can participate in the initial inflammatory response by producing tumor necrosis factor (TNF) and chemokines." (PMID 30149800, 2018). "Infection with the fbp1Δ mutant induced a more robust recruitment of CCR2+ Ly6C+ monocytes and their maturation into mo-DCs compared with H99." (PMID 29317510, 2018). "The chemokine CCL2 is a ligand of the chemokine receptor CCR2, which plays a major role in mobilization of inflammatory monocytes in response to infection." (PMID 30169526, 2018).
infection (continued). "To characterize the influx of CCR2-expressing cells into the liver during infection, we assessed the phenotype of T cells and monocytes/macrophages in uninfected (n = 9) and SIV-infected (n = 9) macaques using flow cytometry." (PMID 29466439, 2018). "Instead, Ly6C+CCR2+CX3CR1+ inflammatory monocytes were identified as important effector cells producing iNOS during secondary infections." (PMID 30346994, 2018). "Altogether, these observations suggest that increased influx of CCR2+ monocytes and their differentiation into mo-DCs upon infection with the fbp1Δ mutant are helpful in the containment of infection." (PMID 29317510, 2018). "Although increased expression of CCL2 during influenza infection has been well-documented, the effects of the CCL2/CCR2 pathway on the pathogenesis of infection are controversial." (PMID 28421067, 2017). "CCR2-depleter mice allowed for the timed removal of monocytes following primary infection but prior to secondary challenge." (PMID 28666021, 2017). "CCL2 was induced in the nasal passages (NPs) upon infection, and co-transfer of in vitro-expanded WT and Ccr2−/− γδT17 cells into infected mice revealed an intrinsic requirement of CCR2 for γδT17 cell accumulation in NP." (PMID 28580944, 2017). "Our results demonstrate that blood-derived CCR2+ monocytes are the definitive source of iNOS+ cells and are essential for rapid parasite elimination at a secondary site in infection." (PMID 28666021, 2017). "The lower levels of Ly6C and CCR2 on RFP+ infected versus uninfected monocytes during secondary infection suggest these cells are undergoing maturation." (PMID 28666021, 2017). "Ly6C expression was much higher on cells from secondary versus primary sites of infection, likely due to the sustained recruitment of these cells in LmLm mice, while CCR2 expression was lower." (PMID 28666021, 2017). "We measured Ly6C and CCR2 expression on CD11b+CD24-CD64+CX3CR1+ putative monocytes on day 3 post-ch to determine the influence of infection and pre-existing immunity on monocyte maturation." (PMID 28666021, 2017). "The levels of IL-1α, IL-1β, IL-6, and IL-18 were unchanged or increased in Ccr2-/- mice during infection, likely reflecting increased cytokine production by other immune cell types in response to the substantial increase in bacterial load." (PMID 28384349, 2017). "To specifically ablate the role of Ly6C++ inflammatory macrophages at the site of infection, we used CCR2-/- mice in which inflammatory monocytes are completely ablated from the site of VACV infection." (PMID 28614386, 2017). "Since Ccr2−/− mice showed a profound defect in PD-L2+ macrophages at 2-wpi, this reinforces the idea that in Ccr2+/+mice an early recruitment of Ly6Chi monocytes occurs during T. crassiceps infection." (PMID 28094319, 2017). "In absence of endogenous γδ T cells, transferred circulating γδT17 cells are able to control infection in a CCR2-dependent manner." (PMID 28580944, 2017). "Because Ccr2-/- mice also exhibited a profound defect in IL-12 production, we next examined secretion of IFNγ into the airway space of Ccr2-/- mice during infection." (PMID 28384349, 2017). "The frequency of CCR2+F4/80+ Ly6Clo/int monocytes steadily increased over the course of infection to reach a plateau of about 70% at d21p.i." (PMID 28892492, 2017). "PGL activated the STING cytosolic sensing pathway in resident macrophages, inducing the production of the chemokine CCL2, which in turn recruited circulating CCR2+ monocytes toward infection." (PMID 28844797, 2017). "Previous studies suggest CCR2+ monocytes undergo maturation to become dendritic cells during late primary infection." (PMID 28666021, 2017). "Ly6C clearly defined inflammatory monocytes at 10 hours post infection (p.i.)and these cells co-expressed CCR2 but were MHCII- and CD11clo." (PMID 28666021, 2017).